MTOR (mechanistic target of rapamycin kinase)
Diseases named in the same sentence as MTOR in open-access papers (continued):
Sharing a sentence is not in itself a finding about the gene and the disease.
adenocarcinoma (continued). "In the current study, we observed that the levels of phosphorylated AKT, phosphorylated mTOR and CA916798 all increased in the drug resistant human adenocarcinoma samples and paralleled with the change of drug resistance." (PMID 23667466, 2013). "For non-intestinal BG adenocarcinoma, a whole-genome case revealed somatic PTEN loss (exons 2–5) together with CCND1 amplification; these findings supported everolimus (mTOR inhibitor) followed by palbociclib (CDK4/6 inhibitor) with radiologic responses under compassionate use." (PMID 41375020, 2025). "Indeed, Akt-mTOR overexpression and hyperactivation could be observed in over 90% of NSCLC adenocarcinoma." (PMID 35831279, 2022). "In total, putative actionable genomic targets (FGFR2, BRAF-V600E, MTOR, NRAS, and KDM6A) were identified in 35% of the cases by OncoKB search, an important finding given the high number of fluent transitions from high-grade IEN to adenocarcinoma at the time of diagnosis (14/17 cases)." (PMID 34205964, 2021). "miR-4735-3p has previously been described to target mammalian target of rapamycin (mTOR)-dependent signaling, by interacting with the long non-coding (lnc) RNA Cancer Susceptibility 2 (CASC2) that plays an important role in inhibiting proliferation and migration of adenocarcinoma cells." (PMID 38162033, 2023).
genetic disorder (40 papers, 2013 to 2025). "Smith–Kingsmore Syndrome (SKS) is a rare genetic disorder resulting from either de novo or inherited gain-of-function mutations in the mTOR pathway, which interfere with the packing of the alpha-helix inhibitory domains and the FAT and kinase domains." (PMID 40358185, 2025). "Our patient fits the spectrum of genetic disorders causing ALPS with dysregulation of the mTOR pathway." (PMID 41026346, 2025). "This is a genetic disorder associated with the mTOR signaling pathway that results in epileptic activity in most individuals afflicted with the disease and is characterized by significant alterations in the relationships between glia and neurons." (PMID 34539347, 2021). "Increasing evidence demonstrates that the constitutive activation of mTOR underlies the overgrowth phenotype of many inherited and sporadic genetic diseases." (PMID 32581239, 2020). "mTORopathies are rare genetic disorders that are induced by neuronal mutations in the mTOR signaling cascade that lead to hyperactivation of the pathway." (PMID 31752127, 2019). "mTORopathies are genetic disorders, which are induced by neuronal mutations in the mTOR signaling cascade that lead to hyperactivation of the pathway." (PMID 31752127, 2019). "Clinical data indicating the efficacy of PI3K or mTOR inhibitors in rare genetic disorders associated with constitutive PI3K pathway activation is sparse but promising." (PMID 31752127, 2019). "Hyperactivation of the mTOR pathway causes a group of rare and ultrarare genetic diseases." (PMID 40426219, 2025). "Tuberous sclerosis complex (TSC) is a genetic disorder that arises from dysfunction in the mTOR pathway, and it is marked by the development of benign tumors in multiple organs, particularly in the brain." (PMID 40358185, 2025). "TSC is a rare multisystem genetic disorder characterized by the development of tumors and caused by mutations in TSC1 or TSC2 genes, leading to dysregulation of the mammalian target of rapamycin (mTOR) pathway." (PMID 41018203, 2025). "TSC is a genetic disorder primarily caused by mutations in the TSC1 or TSC2 genes, leading to the dysregulation of the mechanistic target of rapamycin (mTOR) signaling pathway." (PMID 40558831, 2025). "Mutations in the TSC1 and TSC2 genes lead to dysfunctional mTOR signaling and cause tuberous sclerosis complex (TSC), a genetic disorder that affects multiple organ systems, principally the brain, heart, skin, and kidneys." (PMID 38534508, 2024). "TSC is a genetic disorder characterized by the loss of function of either TSC1 or TSC2 genes, resulting in the hyperactivation of the mechanistic target of rapamycin (mTOR) pathway at the molecular level." (PMID 38089143, 2023). "Tuberous sclerosis complex (TSC) is a genetic disease resulting from mutation in TSC1 or TSC2 and subsequent hyperactivation of mammalian Target of Rapamycin (mTOR)." (PMID 26220190, 2015). "Tuberous sclerosis complex (TSC) is a genetic disorder characterized by multi-system hamartomas, which occur from mutations of the TSC1/TSC2 genes and subsequent overactivation of the mammalian target of rapamycin (mTOR) signaling pathway and dysregulation of cell proliferation." (PMID 36467422, 2022). "We achieved disease control with everolimus (mTOR inhibitor) and bevacizumab (anti-VGEF antibody) in our patient #13 with NF2, showing the importance of targeted therapies in genetic disorders." (PMID 38139220, 2023). "While genetic disorders comprising overgrowth and neurological symptoms give a clear rationale for the application of PI3K/mTOR inhibitors in oncology, the prediction of sensitivity or resistance is still subject to discussion and evaluation." (PMID 31752127, 2019).
cardiac disease (35 papers, 2014 to 2025). "Datasets comparisons in our study showed mTOR perturbations in cardiac disease caused by MPS; therefore, sirolimus could be used." (PMID 36556450, 2022). "mTOR was further investigated, and its association with heart diseases ranged from 0.0004 to 0.8588, which is the overall association score for 49 subtypes of heart diseases." (PMID 32775437, 2020). "In this review, we highlight the dual roles of mTOR in heart disease, where it can either support cardiac function or contribute to disease progression, depending on the context." (PMID 40002810, 2025). "We focus on the molecular mechanisms by which mTOR signaling regulates cardiac diseases and the potential of mTOR inhibitors and related regulatory drugs in preventing these conditions." (PMID 40002810, 2025). "In conclusion, the mTOR signaling pathway remains a highly promising target for therapeutic strategies in heart disease." (PMID 40002810, 2025). "We conclude that the mTOR signaling pathway is a promising therapeutic target for heart disease." (PMID 40002810, 2025). "Furthermore, mTOR inhibitors, such as rapamycin, offer a promising therapeutic approach for both the treatment and prevention of heart disease." (PMID 40002810, 2025). "Given the abundance of evidence supporting the ability of rapamycin to improve cardiac function in CVD driven by dysfunctional autophagy, this mTOR inhibitor is likely to be an effective therapy in highly autophagy dysfunction-driven HIV and HAART associated cardiac disease." (PMID 39086659, 2024). "Additionally, TGFBI has been found as an upstream regulator of mTOR activation in Drosophila models of cardiac disease." (PMID 39041002, 2024). "Similarly, inhibitors of mTOR have been shown to promote cardiomyocyte proliferation and improve heart function in animal models of heart disease." (PMID 37759546, 2023). "The gut microbes and mTOR signaling pathways are both involved in heart disease." (PMID 37511569, 2023). "In addition, the dysregulation of mTOR signaling has been reported in many diseases such as cancer, diabetes, heart disease, and neurological disorders." (PMID 37511569, 2023). "For example, the mammalian target of rapamycin (mTOR) is known as a key regulator of macroautophagy, and its inhibition of mTOR by rapamycin or metformin signaling are known to exert beneficial effects in cardiac disease." (PMID 36671453, 2022). "The AMPK/mTOR pathway was shown to modulate autophagy in liver, renal, and heart disease." (PMID 34510030, 2021). "Notably, PTEN/AKT/mTOR is an important signalling pathway that regulates myocardial autophagy, which plays a key role in heart diseases." (PMID 32714974, 2020). "A unique signaling pathway to regulate the autophagy in cardiac disease is PTEN/AKT/mTOR." (PMID 33260422, 2020). "It has been well established that PDK1 activates Akt/mTOR signaling in severe cardiac disease." (PMID 28536634, 2017). "The role of mTOR in ischaemic heart disease is rather complicated." (PMID 24628978, 2014). "Numerous client proteins of HSP90 have been identified in known cardiac disease pathways, including PI3K/AKT (PKB)/mTOR, and IKKα signaling, all of which are direct and indirect targets of HSP9011." (PMID 39897023, 2025). "Numerous client proteins of HSP90 have been identified in known cardiac disease pathways, including MAPK signaling, PI3K/AKT (PKB)/mTOR, and TNF-α signaling, all of which are direct and indirect targets of HSP90." (PMID 36359837, 2022). "mTOR, a downstream factor of PI3K/AKT pathway, either overexpressed or inhibited induced heart diseases, and the result showed that alcohol extract of Fuzi induced apoptosis in cardiomyocytes through activation of PI3K/AKT/mTOR signaling pathway." (PMID 36324672, 2022). "Numerous client proteins of HSP90 have been identified in known cardiac disease pathways, including MAPK signaling, PI3K/AKT (PKB)/mTOR, and TNF-α signaling." (PMID 36359837, 2022).
cardiac disease (continued). "While there is evidence that mTOR dysregulation in pathological conditions contributes to heart disease, to our knowledge, there have been no studies on the modulation of hERG/IKr by mTOR." (PMID 35897638, 2022). "mTOR is modulated by PI3K/Akt pathway, and the activation of the PI3K/Akt/mTOR pathway could inhibit excessive autophagy and block the cardiac disease progress." (PMID 34604348, 2021). "Taken together, our research showed that JUA could notably reduce the damage cause by ISO via promoting the phosphorylation of PI3K, Akt, and mTOR and inhibiting LC3 conversion, which may be a potential choice for the treatment of heart diseases." (PMID 27293469, 2016).
immune dysfunction (35 papers, 2012 to 2026). "An attractive mechanistic target to investigate conditions of immune dysfunction is the mechanistic/mammalian target of rapamycin (mTOR), which has been directly linked with immune dysfunction and pulmonary damage after injury." (PMID 35955914, 2022). "Activation of the mTOR pathway underlies the pathogenesis of SLE and mTOR contribute to immune disorder in SLE." (PMID 33597869, 2020). "Defects in the genes encoding for the different members of the PI3K/AKT/mTOR/S6K cascade or for molecules interacting with this pathway are frequently associated with immune dysfunction." (PMID 29867948, 2018). "Indeed, these data indicate that interruptions in the mTOR and NFkB pathways prevent the inflammatory sequelae associated with burn injury-induced immune dysfunction and partially restore bacterial resistance." (PMID 36012680, 2022). "Taken together, these data demonstrate a role for mTOR in regulating systemic and local immune dysfunction, with differential effects in the lung and in the periphery, after combined B+I injury." (PMID 35955914, 2022). "For example, rapamycin has been shown to extend life span and ameliorate resilience towards age-related conditions (including immune dysfunction) via the inhibition of the mTOR pathway." (PMID 36346720, 2022). "Inhibition of the mTOR pathway also reduces the production of anti‐dsDNA antibodies produced by B‐cell immune disorders." (PMID 35875970, 2022). "Among the allosteric inhibitors of mTOR, rapamycin and its derivatives were the earliest mTOR inhibitors used in the treatment of immune diseases and tumors." (PMID 36014530, 2022). "In conclusion, we have demonstrated for the first time that mTOR plays a key role in senescence and immune disorders of MSC from SLE patients and MRL/lpr mice." (PMID 27048648, 2016). "Autophagy might be a protective mechanism mediating CD8+ T-cell survival, and mTOR may be a possible target to reverse CD8+ T-cell immune dysfunction." (PMID 34220329, 2021). "Thus, our data demonstrates that RAPA improves the immuno-regulatory capacity of MSCs from SLE patients and indicates the involvement of the mTOR signaling pathway in the immune disorders of SLE patients." (PMID 27048648, 2016). "Furthermore, we show that RAPA reverses the senescence and immune disorders by mTOR signaling pathway." (PMID 27048648, 2016). "We have shown that the mTOR/PPARγ axis is partly responsible for the acute and chronic (analogous to DEARE) immune dysfunction in burn injury, and experiments are underway to determine if MSC-EV can modulate this response in an mTOR-dependent fashion." (PMID 37404812, 2023). "mTOR-PPAR-α axis modification can lead to inflammation and immune dysfunction." (PMID 32775437, 2020). "By sensitizing mTOR-related lymphocyte autophagy, HIT might be more efficient than MCT in resistance to immune dysfunction evoked by oxidative stress." (PMID 24236174, 2013).
psychiatric disorder (30 papers, 2011 to 2025). A disorder characterized by behavioral and/or psychological abnormalities, often accompanied by physical symptoms. "In conclusion, our experiments show that the SZ candidate gene transcript DPYSL2B is regulated by the mTOR pathway and this regulation is perturbed by a 5′-UTR SZ-associated DNR, adding support for mTOR's role in psychiatric disease." (PMID 27801893, 2016). "Understanding the crosstalk mechanisms between mTOR and the clock may help to gain new insights into the pathogenic mechanisms of psychiatric disorders and develop novel therapeutic strategies to treat these diseases." (PMID 36045116, 2022). "Given the known reciprocal relationship between synaptic proteins and protein synthesis in ASD, it is possible that decreased NMDAR function may suppress mTOR signaling and translation of related proteins known to underlie various neurodevelopmental and psychiatric disorders, including ASD." (PMID 34594187, 2021). "In this review, we focused on the role of mTOR signaling and the related aberrant neurogenesis in psychiatric disorders." (PMID 38365306, 2024). "In conclusion, this systematic and comprehensive review has focused on the critical role of mTOR signaling in psychiatric disorders and the effects of antipsychotic medications." (PMID 38365306, 2024). "Since perturbations in mTOR signaling are implicated in multiple neurodevelopmental, neurodegenerative and psychiatric disorders that affect dopaminergic function, it is important to understand how mTOR controls DA neuron cytoarchitecture and physiology." (PMID 35881440, 2022). "Here, we review recent progress in understanding the trilateral interactions and propose an “interaction triangle” model between mTOR signaling, the circadian clock, and psychiatric disorders (focusing on ASD and MD)." (PMID 36045116, 2022). "Whereas the underlying mechanisms remain to be fully elucidated, increasing clinical and preclinical evidence support significant crosstalk between mTOR signaling, the circadian clock, and psychiatric disorders." (PMID 36045116, 2022). "Increasing evidence support an “interaction triangle” model between the circadian clock, mTOR signaling, and psychiatric diseases." (PMID 36045116, 2022). "There is abundant evidence linking mTOR signaling to synaptic plasticity, memory, and psychiatric disorders." (PMID 27067128, 2016). "In this paper, we provide an overview of research on the characterization of the regulation of PI3K/AKT/GSK3/mTOR signaling from the viewpoint of pathogenesis on mental illnesses." (PMID 23320155, 2012). "Elucidating the neurobiology of the PI3K-AKT/mTOR signaling pathway in psychiatric disorders and its actions in response to antidepressants will help us better understand brain development and quickly identify new therapeutic targets for the treatment of these mental illnesses." (PMID 38365306, 2024). "Although the underlying mechanisms remain to be fully understood, the interactions between the circadian clock, mTOR signaling, and psychiatric disorders appear to be significant in ASD and MD and should be considered in basic research and pharmaceutical developments." (PMID 36045116, 2022). "Hyperactive mTOR and mGluR5 signaling are implicated in ASD and other psychiatric disorders." (PMID 32179875, 2020). "Emerging evidence indicates that even subtle defects in the mTOR pathway may produce severe effects, which are evident as neurological and psychiatric disorders." (PMID 30061532, 2018). "In this review, we will first introduce the mammalian circadian system and a role for mTOR signaling in the mammalian circadian clock, and then we will discuss recent progress on our understanding of circadian and mTOR dysfunctions in highly prevalent psychiatric disorders, ASD and MD." (PMID 36045116, 2022).
psychiatric disorder (continued). "As mTOR inhibitors are FDA approved drugs, understanding the interactions between the circadian clock, mTOR, and psychiatric disorders may open new therapeutic avenues to regulate the brain clock function and treat psychiatric diseases." (PMID 36045116, 2022). "Accordingly, 5‐HT6 receptor antagonism will not reproduce the severe side effects induced by mTOR inhibitors such as rapamycin, which limit their clinical development for the treatment of psychiatric diseases." (PMID 32329240, 2020). "In a second stage, proteomic analysis of rapamycin treatment effects were investigated to identify down-stream effects of mTOR-pathway inhibition in the hope to gain new insights into the molecular underpinnings of social impairments in ASD and other psychiatric disorders." (PMID 28775826, 2017).
infectious disease (28 papers, 2012 to 2026). A disorder directly resulting from the presence and activity of a microbial, viral, or parasitic agent in humans. "It has been demonstrated that mTOR plays a role in immune defense against pathogens by regulating necroptosis, which provides a possible target for treating infectious diseases." (PMID 38164133, 2023). "At the same time, activating autophagy through the PI3K/AKT/mTOR pathway is a common mechanism for treating infectious diseases." (PMID 34483936, 2021). "A thorough understanding of how mTOR impacts lymphoid cells in pathogen defense will provide the necessary base for developing therapeutic interventions for infectious diseases." (PMID 27242787, 2016). "Both MCV-negative and MCV-positive tumors responded to MLN0128 treatment suggesting mTOR is dysregulated in both infectious and non-infectious tumors." (PMID 26536665, 2016). "In the context of the apparently contrasting immunological outcomes of mTOR's function in T cells and APCs, designing drugs capable of modulating the mTOR signaling axis to fight against infectious diseases becomes especially challenging." (PMID 23028309, 2012). "In the solid organ transplant infectious disease field, data have begun to emerge that certain mTOR inhibitors (used as anti-organ rejection medications) may have anti-viral properties, reducing the risk of some viral reactivation syndromes." (PMID 36171757, 2022). "In addition, mTOR inhibition in combination with the modulation of environmental cues using agents such as IL-2 might lead to new strategies for the treatment of infectious diseases or immunosuppressive tumors." (PMID 30619313, 2018). "BCG predominantly induced a demethylation in genes related to mTOR, Myc, E2F, IL-2–STAT5, and infectious disease pathways." (PMID 39872813, 2025). "Collectively, the mTOR signaling pathway and RBP TTP could be promising therapeutic targets in infectious disease especially in Mtb infection." (PMID 39114448, 2024).